MYC (MYC proto-oncogene, bHLH transcription factor)
Diseases named in the same sentence as MYC in open-access papers (continued):
Sharing a sentence is not in itself a finding about the gene and the disease.
brain tumor (continued). "Not surprisingly, given the capacity to increase growth and proliferation, MYC is frequently upregulated in primary brain tumours (reviewed elsewhere,)." (PMID 33092025, 2020). "We therefore propose using these inhibitors in combination for treating MYC-dependent, aggressive pediatric brain tumors." (PMID 29511348, 2018). "It is therefore tempting to suggest combining WNT antagonists to open up the BBB with MYC therapy in order to more effectively deplete MYC-dependent brain tumors and block their recurrence." (PMID 28333115, 2017). "In this review, we explore the roles of MYC oncoproteins and their molecular targets during the formation, maintenance, and recurrence of childhood brain tumors." (PMID 28333115, 2017). "We will also describe ways of modeling MYC-driven brain tumors and highlight recent findings describing the attempts to target MYC proteins." (PMID 28333115, 2017). "By summarizing the data reported from quite a few sophisticated MYC-driven brain tumor models, it is increasingly evident how context-dependent these various cancer processes are." (PMID 28333115, 2017). "In this review, we highlighted the mechanisms behind MYC-driven tumor initiation, maintenance and recurrence with a focus on malignant childhood brain tumors." (PMID 28333115, 2017). "It is thus interesting to postulate that HEATR1 may also be a MYC target during brain tumour development." (PMID 38225354, 2024). "MYC and MYCN have been found to have specific and different Arf suppression mechanisms and effects in brain tumors and amplifications are associated with different tumor groups in brain tumors." (PMID 37533331, 2023). "We also found that the metabolism of MYC-amplified cell lines differed from orthotopic brain tumors in vitro and in flank tumors, suggesting that analyses conducted in vitro or in flank tumors may miss key vulnerabilities." (PMID 35267619, 2022). "The oncogene MYC is required for upregulation of the mevalonate pathway in brain tumor cells, and the upregulation of this pathway forms a positive feedback that increases the expression of the microRNA miR-33b, which in turn increases expression of MYC." (PMID 33530546, 2021). "Additionally, a MYC-subgroup has recently been identified in pineoblastoma, a rare but quite frequently metastatic, pediatric brain tumor of the pineal gland with modest overall survival despite intensive therapy." (PMID 33585252, 2020). "Furthermore, we established cell lines from Arf-depleted MYC-driven brain tumors." (PMID 36869047, 2023). "For instance, MYC and EGFR have been reported to be critical for maintenance of the brain tumor-initiating cells in adult glioblastoma." (PMID 39419964, 2024). "Since the parental PLX038 is already in clinical trials, it would be a straightforward path to translate these experiments to trials on human brain tumors; indeed, a trial of PLX038 in MYC-amplified CNS tumors has been initiated (NCT06161519)." (PMID 38898077, 2024). "Among all the tested combinations, we observed reduced mice survival with Gfi1 + c-MYC (GM) and Otx2 + c-MYC (OM) genes overexpression and formation of brain tumors." (PMID 31996670, 2020). "Previous evidence indicated that silencing MYC significantly reduced both mRNA and protein levels of PRPS1 in brain tumor-initiating cells, and chromatin immunoprecipitation assay showed that MYC interacted with the promoter regions of PRPS1 gene." (PMID 31443513, 2019). "Since Palbociclib treatment only suppressed MYCN in combination with JQ1, we decided from now on to focus on Milciclib alone or in combination with JQ1 for targeting MYC and MYCN-driven brain tumors." (PMID 29511348, 2018). "Elevated c-MYC/MYCN initiates and drives tumorigenesis in many in vivo model systems of pediatric brain tumors." (PMID 28333115, 2017). "For example, a decrease in expression of c-MYC, TIN2, DKC1, and RFC1 genes which are positive regulators of telomerase, was seen in MST-312 treated brain tumour cells." (PMID 25307264, 2014).
brain tumor (continued). "MYC is overexpressed in brat NSC lineages, and its inhibition reduces brat brain tumour growth." (PMID 38225354, 2024). "We further show that HEATR1 binds the master ribogenesis and cell growth regulator MYC and promotes its localisation to ribogenesis sites, suggesting a mode of action to enhance ribogenesis during early TIC development stimulating the transition into brain tumour growth." (PMID 38225354, 2024). "However, although not discussed in this review, better MYC drugs would still meet an unavoidable obstacle in brain tumor therapy—the blood–brain barrier (BBB)." (PMID 28333115, 2017). "It is not known whether the co-existence of high levels of onco-MYC and tumor suppressor-let-7 had any impact in the carcinogenesis of brain tumors." (PMID 27409345, 2016). "Even though we observed down-regulation in expression of MYC gene, the level of TERT protein and gene expression was not altered in MST-312 treated brain tumour cells." (PMID 25307264, 2014).
angiosarcoma (65 papers, 2012 to 2025). A malignant tumor arising from the endothelial cells of the blood vessels. "In our dataset, MYC mutations occurred significantly more frequently in the breast compared to liver angiosarcomas (p = 1.376 × 10−3)." (PMID 41301029, 2025). "The overexpression of the miR-17-92 cluster in MYC-amplified angiosarcomas was associated with the downregulation of thrombospondin-1 (THBS1), a glycoprotein that inhibits angiogenesis." (PMID 39594601, 2024). "Radiation- and lymphedema-associated angiosarcomas were associated with MYC gene amplification, whereas primary angiosarcomas of the breast showed a high rate of PIK3CA-activating mutations." (PMID 34545273, 2021). "For radiation-associated and lymphedema-associated angiosarcoma high-level amplification of the proto-oncogene MYC is regarded one of the most common genetic alterations." (PMID 34040639, 2021). "MYC upregulation is closely associated with radiation-related angiosarcoma due to H3K27me3 deficiency." (PMID 35008848, 2021). "V-Myc Avian Myelocytomatosis Viral Oncogene Homolog (MYC) amplified tumors are common in radiation-induced and lymphedema-associated angiosarcomas." (PMID 28056866, 2017). "MYC amplifications were significantly more frequent in angiosarcomas known to be associated with previous radiation (7/7 = 100%) than in those with no history of prior irradiation (1/27 = 4%; p < 0.0001)." (PMID 26440310, 2015). "The finding of MYC amplification in this case of AVG-associated angiosarcoma expands the spectrum of recognized clinicopathologic subtypes of angiosarcoma bearing this aberration and suggests they share similar pathogenesis." (PMID 26682080, 2015). "We identified a number of known genetic alterations in angiosarcomas, including MYC and KLT4 amplifications, RAS mutations, inactivating PTPRB mutations and an activating PLCG1 mutation." (PMID 26440310, 2015). "In this review, we will critically analyze recent advances in our understanding of angiosarcomas, specifically dealing with transcriptional signatures associated with aberrant angiogenesis as well as MYC amplifications in secondary angiosarcomas." (PMID 25374893, 2013). "MYC mutations have been associated with secondary angiosarcomas." (PMID 41301029, 2025). "In angiosarcomas secondary to radiation, MYC mutations have been well documented." (PMID 41301029, 2025). "All these findings suggest that MYC can be considered a hallmark of secondary angiosarcoma and may have implications for both the diagnosis and treatment of these tumors." (PMID 39202050, 2024). "Additonally, MYC amplification is a recurrent genetic mutation in secondary angiosarcoma." (PMID 28716069, 2017). "Perhaps this mechanism can account for MYC gene aberration in foreign body-associated angiosarcoma." (PMID 26682080, 2015). "The presence of c-MYC amplification may therefore be an additional diagnostic tool in the diagnosis of secondary angiosarcoma." (PMID 24078891, 2013). "Additionally, MYC amplification was a recurrent finding in the breast angiosarcoma cases in our cohort; this finding is consistent with prior studies, which have found the consistent presence of high-level MYC amplification in radiation-associated angiosarcoma." (PMID 38791996, 2024). "Moreover, we also examined MYC amplification using fluorescent in situ hybridisation (FISH) as there is an evidence in literature that high-level MYC gene amplifications (at 8q24.21) occur in majority of post-irradiation and chronic lymphoedema-associated angiosarcomas." (PMID 37349756, 2023).
angiosarcoma (continued). "Since MYC-amplified angiosarcoma is associated with lower expression of thrombospondin-1 (THBS1), MYC amplification may be important in the angiogenic phenotype of angiosarcoma through upregulation of the miR-17-92 cluster, which downregulates THBS1 expression." (PMID 25165708, 2014). "Immunohistochemistry for FLI-1 will be positive, and MYC can be positive in cases of radiation- or lymphedema-induced angiosarcomas." (PMID 40895846, 2025). "The detection of MYC amplification through FISH can aid in distinguishing angiosarcoma from other vascular lesions, particularly in challenging cases." (PMID 40004808, 2025). "Fluorescence in situ hybridization (FISH) is a useful technique for detecting MYC gene amplification in angiosarcoma samples." (PMID 40004808, 2025). "Studies have shown that MYC amplification is almost exclusively found in radiation-related angiosarcoma." (PMID 40004808, 2025). "Stabilization of MYC protein in thymic lymphomas by mutations in E3-ligases (that otherwise target MYC degradation) also likely contributes to a more variable ratio of MYC RNA to protein level than is seen in hemangiosarcomas." (PMID 40970130, 2025). "Weaker correlation of γH2AX and MYC in thymic lymphomas than in hemangiosarcomas likely reflects the special biology of lymphocytes." (PMID 40970130, 2025). "In our exploration of the genetic landscape of canine hemangiosarcoma, we focused on identifying copy number alterations (CNAs) within genes previously associated with the disease, including CDKN2A/B, VEGFA, KDR, SKI, MYC, and KIT." (PMID 39872607, 2024). "A high-level gene amplification pattern was detected in 25% of radiation-induced angiosarcomas and in one post-lymphedema angiosarcoma analyzed and again co-amplified with MYC." (PMID 39202050, 2024). "MYC-positive cutaneous angiosarcomas demonstrate overexpression of atypical Protein Kinase C lambda/iota (aPKCλ)." (PMID 38826780, 2024). "Among the genes historically linked to hemangiosarcoma, alterations in CDKN2A/B, KDR, MYC, and KIT were prominently identified in our study, underscoring their potential roles in the pathogenesis of this cancer in dogs." (PMID 39872607, 2024). "Mutations in the FoxO1 protein (FoxO1Ser218) can impair its ability to activate miR-34, leading to MYC overexpression and increased cell proliferation in primary cutaneous angiosarcomas." (PMID 38826780, 2024). "miR-17-92 cluster: The miR-17-92 cluster, a well-known oncogenic miRNA cluster, is significantly upregulated in angiosarcoma, especially in cases with MYC amplification." (PMID 39594601, 2024). "MYC amplification, observed in both primary and secondary angiosarcomas, can also indirectly influence angiosarcoma development." (PMID 38826780, 2024). "IHC staining that is positive for c-MYC has near 100% specificity for radiation-induced angiosarcoma and can be used to differentiate the two lesions." (PMID 37232796, 2023). "MYC gene amplification as a result of recurrent genetic alterations on chromosome 8q24.21 is highly indicative of secondary angiosarcoma." (PMID 35456944, 2022). "In angiosarcomas that develop in the setting of chronic lymphedema or radiation, there is usually strong positivity for MYC." (PMID 36135073, 2022). "Frequently encountered alterations include MDM2 amplification for well-/dedifferentiated liposarcomas, MYC amplification for radiation induced angiosarcoma or segmental chromosomal deletions on chromosome 22q encompassing SMARCB1 for rhabdoid tumours." (PMID 33479225, 2021). "MYC gene amplification was related to exposure to ultraviolet and sunlight and was found in more than 80% of radiation-induced angiosarcoma cases." (PMID 34068344, 2021). "In 10 angiosarcomas with known copy number data, the 3 samples with MYC amplifications all had developed post radiotherapy." (PMID 34040639, 2021).
angiosarcoma (continued). "MYC upregulation was observed in secondary angiosarcoma and to a lesser extent in primary angiosarcoma." (PMID 35008848, 2021). "MYC is a multifunctional nuclear protein that is related to the cell cycle, apoptosis, angiogenesis, and metastasis of angiosarcoma." (PMID 35008848, 2021). "Among angiogenesis genes, MYC plays a role especially in secondary angiosarcoma characterized by the frequent amplification of the region at chromosome 8q24 where MYC is located." (PMID 34068344, 2021). "MYC amplification with expression of the corresponding protein is predominantly seen in cases secondary to radiation or UV-damage in contrast to primary angiosarcomas being rarely MYC amplified." (PMID 31950476, 2020). "MYC gene amplification has been demonstrated as a distinctive feature of radiation-induced angiosarcoma." (PMID 29765529, 2018). "Of note, whilst secondary angiosarcomas that arise due to prior irradiation usually carry an amplification of the oncogene MYC, this alteration is less common in primary angiosarcomas." (PMID 28895916, 2017). "Recently, Shon and his colleagues confirmed the presence of both MYC amplification and MYC overexpression in a minority of primary angiosarcomas." (PMID 28716069, 2017). "Other than miR-497-5p, the miR-17-92 cluster is significantly upregulated in MYC proto-oncogene (MYC)-amplified angiosarcoma." (PMID 28895916, 2017). "Recent studies have shown that high-level amplification of MYC oncogene on chromosome 8q24.21 is specific for secondary angiosarcoma after radiation or lymphedema." (PMID 26462621, 2015). "Both FLT4 and MYC gene abnormalities can potentially be used as molecular diagnostic tool to distinguish from atypical vascular lesions (AVL) and secondary angiosarcoma." (PMID 26462621, 2015). "Recent findings of frequent high-level MYC gene amplification in angiosarcomas suggest a genetic basis for the disease." (PMID 26682080, 2015). "MYC copy number increases were found in all seven tumors known to have arisen post-irradiation, strongly supporting MYC amplifications being a major event in this angiosarcoma subtype." (PMID 26440310, 2015). "Focal MYC amplifications were identified in 8 (24%) angiosarcomas, VEGFR2 (KDR) amplifications in 4 (12%) tumors." (PMID 26440310, 2015). "MYC amplification was identified in 3 out of 6 primary angiosarcomas and in 8 out of 12 secondary angiosarcomas by array-comparative genomic hybridization (aCGH) and FISH analysis." (PMID 25165708, 2014). "High level gene amplification of MYC is also a distinguishing feature of cutaneous secondary angiosarcomas, which develops after chronic lymphoedema or irradiation." (PMID 25574331, 2014). "Limited data exists evaluating the molecular mechanisms controlling angiosarcomas, however a wealth of recent publications have shown that key features of angiosarcomas include aberrant angiogenic signaling, increased oxidative stress, and MYC amplification." (PMID 25374893, 2013). "Reduced expression of thrombospondin-1 (THBS1) has been reported in MYC-amplified angiosarcomas (more on MYC amplifications in angiosarcomas below), and its expression is either downregulated or lost across many cancers." (PMID 25374893, 2013). "As standard chemotherapy and even novel anti-angiogenic treatments have largely failed patients stricken with angiosarcoma, strategies for exploiting MYC dependency in angiosarcoma tumors are an attractive disease-specific goal." (PMID 25374893, 2013). "Amplification of the MYC gene is observed in approximately 23% of angiosarcoma cases." (PMID 40004808, 2025).